RNU6-910P (RNA, U6 small nuclear 910, pseudogene)
Gene: Small nuclear RNA gene on chromosome 3 (196,341,609 to 196,341,715, reverse strand). Ensembl gene ENSG00000212146.
Homologues: Orthologues: chimpanzee U6 (95% identical), macaque U6 (87% identical), pig U6 (76% identical), mouse Gm23864 (75% identical). Paralogues in human: RNU6-16P (81% identical), RNU6-12P (80% identical), RNU6-13P (80% identical), RNU6-22P (80% identical), RNU6-32P (80% identical), RNU6-726P (80% identical), RNU6-968P (80% identical), RNU6-1 (79% identical), RNU6-11P (79% identical), RNU6-17P (79% identical), RNU6-18P (79% identical), RNU6-2 (79% identical), and 1288 more.